SEMA7A (semaphorin 7A (JohnMiltonHagen blood group))
Diseases named in the same sentence as SEMA7A in open-access papers (continued):
Sharing a sentence is not in itself a finding about the gene and the disease.
peritonitis (3 papers, 2021 to 2025). Inflammation of the peritoneum (tissue that lines the abdominal wall and covers most of the organs in the abdomen). "Paradoxical to these studies, in acute sepsis and peritonitis, a protective role of Sema7a has been identified through immunomodulation." (PMID 40114253, 2025). "Sema7a has been shown as crucial for the resolution of severe inflammation, through polarization of macrophages to a pro-resolving phenotype in acute peritonitis." (PMID 40114253, 2025). "Here, we also found a significant increase in serum SEMA7A levels following the induction of peritonitis." (PMID 38094294, 2023). "In a final attempt to come closer to an explanation of the described results, we focused on the expression of SEMA7A target receptors in the peritoneum during ZyA-induced peritonitis." (PMID 38094294, 2023). "The research involved inducing peritonitis in SEMA7A knockout (SEMA7A-/-) and wild-type (WT) animals through Zymosan A (ZyA) injection." (PMID 38094294, 2023). "The differential responses in peritonitis and intestinal inflammation suggest that SEMA7A's function is significantly influenced by the expression and distribution of its target receptors within different organ systems." (PMID 38094294, 2023). "Using a murine peritonitis model, we demonstrated that Sema7A induces an antiinflammatory and proresolving phenotype in not only monocyte-derived MΦs but also resident MΦs." (PMID 33637648, 2021). "In this regard, the efferocytosis rate of apoptotic PMNs was strongly reduced in Sema7A−/− mice, suggesting that Sema7A promoted an accelerated-resolution phenotype in acute peritonitis." (PMID 33637648, 2021). "Next, we exposed Sema7A−/− mice and their littermate controls to ZyA-induced peritonitis." (PMID 33637648, 2021). "Next, we quantified whether SEMA7A is induced or repressed during peritonitis." (PMID 38094294, 2023).
Sepsis (3 papers, 2021 to 2025). Sepsis is defined as life-threatening organ dysfunction caused by a dysregulated host response to infection. "In our sepsis cohort, SEMA kinetics were linked to sepsis complications with SEMA3A, SEMA3C, SEMA4D and SEMA7A associated with mortality." (PMID 40869413, 2025). "While SEMA3A was decreased, SEMA3C, SEMA3F, SEMA4D, and SEMA7A were increased in sepsis patients." (PMID 39770766, 2024). "To more closely mimic sepsis, a life-threatening illness, we determined whether Sema7A could influence the mortality of mice afflicted with polymicrobial sepsis." (PMID 33637648, 2021). "In conclusion, we have shown that patients with sepsis have different serum concentrations of SEMA3A, SEMA3C, SEMA3F, SEMA4D, and SEMA7A compared to healthy controls and that their kinetics during sepsis correlate with disease severity and outcomes." (PMID 39770766, 2024). "Patients with sepsis had significantly higher serum levels of SEMA3C, SEMA3F, SEMA4D, and SEMA7A and a significantly lower SEMA3A." (PMID 39770766, 2024). "While SEMA3A was decreased, SEMA3C, SEMA3F, SEMA4D, and SEMA7A were increased in sepsis patients, and all analyzed SEMA showed good accuracy in identifying patients with sepsis." (PMID 39770766, 2024). "Furthermore, the kinetics of SEMA were related to sepsis complications; SEMA3A, SEMA3C, SEMA3F, and SEMA4D were related to respiratory failure; SEMA3C and SEMA7A were related to acute kidney injury, while SEMA3C and SEMA3F were related to septic shock." (PMID 39770766, 2024).
Alzheimer disease (2 papers, 2015 to 2024). A progressive, neurodegenerative disease characterized by loss of function and death of nerve cells in several areas of the brain leading to loss of cognitive function such as memory and language. "Additionally, Sema5A and/or Sema7A are involved in the regulation of neurogenesis in adults, and dysfunction is also associated with Alzheimer’s disease-like phenotypes." (PMID 38666924, 2024).
autoimmune disease (2 papers, 2017 to 2023). A disorder resulting from loss of function or tissue destruction of an organ or multiple organs, arising from humoral or cellular immune responses of the individual to their own tissue constituents. "SEMA7A is closely associated with the pathogenesis of various autoimmune diseases, inflammation-related diseases, and tumors." (PMID 37958549, 2023). "Therefore, our results provide a further rationale for prospective clinical studies designed to evaluate whether Sema7A provides effective therapeutic activities in RA and other autoimmune diseases." (PMID 28109308, 2017).
colorectal cancer (2 papers, 2022 to 2024). A primary or metastatic malignant neoplasm that affects the colon or rectum. "In this study, we aimed to evaluate the expression of SEMA7A, SEMA4D, ADAM8, and ADAMTS10 in colorectal cancer (CRC) in relation to the mutational landscape of KRAS, NRAS, BRAF, PIK3CA, and AKT genes, microsatellite instability (MSI) status, and clinicopathological features." (PMID 39329961, 2024).
epilepsy (2 papers, 2007 to 2020). A brain disorder characterized by episodes of abnormally increased neuronal discharge resulting in transient episodes of sensory or motor neurological dysfunction, or psychic dysfunction. "Furthermore, the mechanism underlying Sema7A‐related inflammation in epilepsy was explored." (PMID 31179640, 2020). "The function and mechanisms of Sema7A in epilepsy were investigated using a lentivirus delivery system to regulate the level of Sema7A protein expression." (PMID 31179640, 2020). "This study is the first to explore the relationship between Sema7A and epilepsy and to further explore the inflammatory and morphological mechanisms of Sema7A‐mediated seizures in epilepsy." (PMID 31179640, 2020). "As this study is the first on the role of Sema7A in epilepsy, further investigations are needed to elucidate the possible mechanistic role of this protein in epilepsy." (PMID 31179640, 2020). "BDA tracing experimental results showed that the mossy fiber projections were increased in epileptic rats of the Sema7A overexpression group but decreased in the knockdown group, indicating that Sema7A can promote mossy fiber growth in epilepsy." (PMID 31179640, 2020). "To further investigate the expression of Sema7A in epilepsy, we detected the expression level of Sema7A in PTZ‐kindled rat models of epilepsy." (PMID 31179640, 2020). "In our study, we aimed to investigate the expression patterns of Sema7A in epilepsy and further explore the roles of Sema7A in the regulation of seizure activity and the inflammatory response in PTZ‐kindled epileptic rats." (PMID 31179640, 2020). "Second, to explore the role of Sema7A in the regulation of seizure activity, we conducted epilepsy‐related behavioral experiments after knockdown and overexpression of Sema7A in the rat hippocampal dentate gyrus (DG)." (PMID 31179640, 2020). "Sema7A plays a critical role in epilepsy and could be a potential therapeutic target for this neurological disorder." (PMID 31179640, 2020). "First, we measured the Sema7A expression levels in patients with temporal lobe epilepsy (TLE) and in rats of a PTZ‐kindled epilepsy rat model." (PMID 31179640, 2020). "In conclusion, our study demonstrates that Sema7A is upregulated in the brain tissues of refractory TLE patients and PTZ‐kindled model rats and plays an important role in epilepsy." (PMID 31179640, 2020). "Sema7A may mediate seizure activity by regulating the ERK‐mediated inflammatory response and mossy fiber growth in epilepsy." (PMID 31179640, 2020).
Kallmann syndrome (2 papers, 2021 to 2022). Kallmann syndrome (KS) is a developmental genetic disorder characterized by the association of congenital hypogonadotropic hypogonadism (CHH) due to gonadotropin-releasing hormone (GnRH) deficiency, and anosmia or hyposmia (with hypoplasia or aplasia of the olfactory bulbs). "Mutations in SEMA7A are associated with decreased bone mineral density and Kallmann syndrome." (PMID 35938531, 2022). "SEMA7A mutations are associated with vertebral fracture and Kallmann syndrome." (PMID 34585848, 2021). "Moreover, mutations in SEMA7A are associated with several disorders, such as Kallmann syndrome." (PMID 35938531, 2022). "Mutations in SEMA7A are associated with decreased bone mineral density (BMD) and Kallmann syndrome in humans." (PMID 34585848, 2021).
lung adenocarcinoma (2 papers, 2021 to 2024). A carcinoma that arises from the lung and is characterized by the presence of malignant glandular epithelial cells. "Based on this study, Sema7A levels may be considered a biomarker of mTOR pathway activation, useful for guiding therapeutic decisions in EGFR-dependent lung adenocarcinoma patients." (PMID 33537086, 2021).
metastatic disease (2 papers, 2014 to 2020). "This raises the possibility that metastatic tumors express higher levels of SEMA7A." (PMID 24550834, 2014).
oral squamous cell carcinoma (2 papers, 2015 to 2024). "We present the results of a comprehensive analysis of molecular/cellular subtypes of SEMA7A in oral squamous cell carcinoma (OSCC) that are linked functionally and contribute clinically to tumoral progression and prognosis in OSCCs." (PMID 26378920, 2015). "Of them, SEMA7A has been reported to have a chemotactic activity in neurogenesis and to be an immunomodulator; however, little is known about the relevance of SEMA7A in the behaviors of oral squamous cell carcinoma (OSCC)." (PMID 26378920, 2015).
Parkinson disease (2 papers, 2023 to 2024). A progressive degenerative disorder of the central nervous system characterized by loss of dopamine producing neurons in the substantia nigra and the presence of Lewy bodies in the substantia nigra and locus coeruleus. "Recent evidence indicates that semaphorin 7A (SEMA7A) is implicated in various neurodegenerative diseases, but whether it plays a role in Parkinson's disease (PD) remains unclear." (PMID 36705403, 2023). "The knockdown of SEMA7A was shown to inhibit apoptosis and inflammation by activating PPAR-γ and inactivating MAPK in Parkinson’s disease." (PMID 38665091, 2024).
steatosis (2 papers, 2022 to 2024). Increased lipid within the cytoplasm of cells. "SEMA7A has been shown to be protective against high-fat diet-induced obesity, while SEMA7A deletion resulted in increased steatosis and insulin resistance in a mouse model." (PMID 38336825, 2024).
temporal lobe epilepsy (2 papers, 2020 to 2024). A localization-related (focal) form of epilepsy characterized by recurrent seizures that arise from foci within the temporal lobe, most commonly from its mesial aspect. "Similarly, elevated Sema7A expression has been observed in brain tissue of patients with temporal lobe epilepsy as well as in rat epileptic models." (PMID 39152101, 2024).
thrombosis (2 papers, 2021 to 2024). "In our study, we observed a positive association of Sema7A/CD163 in thrombosis with poor prognosis of AIS." (PMID 38373967, 2024).
vasculitis (2 papers, 2024 to 2025). "Taken together, our findings suggest a potential pathological role of sSema7A in KD vasculitis and indicate a close association between Sema7A and the severity of KD." (PMID 38678170, 2024). "Sema7A has been reported to mediate endothelial cell destabilization, activation of immune cells, and cytoskeletal remodeling, all of which are closely associated with vasculitis." (PMID 38678170, 2024). "A recent report showed that Sema7A contributes to the progression of KD vasculitis by promoting endothelial permeability and inflammation through a Plexin C1- and Integrin β1-dependent pathway." (PMID 39857904, 2025). "Based on the KD cell model with upregulated plexin C1 and integrin β1 and the important role of inflammatory activation of vascular endothelial cells in KD vasculitis, we explored the action of Sema7A on inflammation in HCAECs." (PMID 38678170, 2024). "Sema7A is involved in the progression of KD vasculitis by promoting endothelial permeability and inflammation through a plexin C1 and integrin β1-dependent pathway." (PMID 38678170, 2024). "Our findings suggest that the Sema7A/plexin C1/integrin β1 axis is involved in the progression of KD, and Sema7A may serve as a novel prognostic and therapeutic candidate for KD vasculitis." (PMID 38678170, 2024). "Firstly, this study lacks in vivo experiments to explore the roles of Sema7A in KD vasculitis." (PMID 38678170, 2024).
acute myocardial infarction (1 paper, 2020). Necrosis of the myocardium, as a result of interruption of the blood supply to the area. "Here, we show that platelet–neutrophil complexes (PNCs) are increased in patients with acute myocardial infarction and that this is associated with increased levels of neuronal guidance protein semaphorin 7A (SEMA7A)." (PMID 32161256, 2020).
adrenal tumors (1 paper, 2025). "Immunohistochemistry (IHC) staining of ACC tissues shows a bimodal distribution of SEMA7A in ACC patients with lower levels in normal adrenal tissues and benign adrenal tumors and high protein levels in ACC." (PMID 40647379, 2025).
adrenocortical adenoma (1 paper, 2025). "To compare SEMA7A transcripts and protein expression, we first used tissue microarray slides to determine whether SEMA7A protein expression could be measured in normal adrenal gland (n = 6), adrenocortical adenoma (n = 27) and ACC (n = 14) tumor tissues." (PMID 40647379, 2025).
allergic asthma (1 paper, 2023). A asthma with a basis in a pathological type I hypersensitivity reaction. "Then, whether the expression of Sema7a was associated with pathological features of allergic asthma was evaluated." (PMID 38022556, 2023). "Nevertheless, whether Sema7a has a role in the development of allergic asthma remains obscure." (PMID 38022556, 2023). "Thus, Sema7a and its integrin-β1 receptor may be potential therapeutic targets for allergic asthma." (PMID 38022556, 2023).
allergic disease (1 paper, 2023). An immune response that occurs following re-exposure to an innocuous antigen, and that requires the presence of existing antibodies against that antigen. "Because eosinophils play an important role in the transmission of airway allergic diseases such as asthma, we hypothesize that Sema7a may be a critical cytokine in the development of allergic airway diseases in asthma." (PMID 38022556, 2023).
Anxiety (1 paper, 2025). Intense feelings of nervousness, tension, or panic often arise in response to interpersonal stresses. "Through identifying and targeting potential biomarkers that regulate the TME, such as SEMA7A, collagen, and COX-2, we can further our understanding of contributing factors to DCIS invasion and begin to address overtreatment and anxiety in DCIS patients with safer, less toxic, interventions." (PMID 40470186, 2025).
Arthritis (1 paper, 2017). Inflammation of a joint. "For the CIA treatment studies, mice with established clinical arthritis (an average score of 4) were randomized and given an injection with anti-Sema7A antibody or a control antibody." (PMID 28109308, 2017). "Indeed, we observed that the arthritis scores and paw swelling in mice treated with anti-Sema7A antibody were significantly reduced compared with those in control mice, and the reduction in the arthritis scores was attenuated in mice treated with half a dose of the antibody." (PMID 28109308, 2017). "Blocking Sema7A in CIA exerted favorable therapeutic effects and achieved a dramatic arrest in disease progression, as confirmed by the clinical, histopathological, and immunological manifestations of arthritis." (PMID 28109308, 2017).
asthma (1 paper, 2023). "The level of Sema7a in patients with asthma was significantly higher than that in healthy subjects (P < 0.01)." (PMID 38022556, 2023). "With further studies, Sema7a or integrin-β1 is expected to be used as an immunotherapeutic treatment target for asthma." (PMID 38022556, 2023). "First, our study identified, for the first time, the expression of Sema7a in serum and found these to be enhanced in asthma patients (P < 0.01)." (PMID 38022556, 2023). "Stimulated by acetylcholine, R was significantly enhanced and C was decreased in the asthma group compared with the control group (P < 0.01), while R was significantly decreased and C was enhanced in the anti-Sema7a group mice compared with the asthma group mice (P < 0.01)." (PMID 38022556, 2023). "In conclusion, the present study demonstrated that Sema7a may contribute to asthma AR pathology by affecting HBEC function and airway EMT." (PMID 38022556, 2023). "In summary, Sema7a may be involved in asthma airway EMT through the FAK/ERK1/2 signaling pathway." (PMID 38022556, 2023). "Sema7a may play an important role in asthma airway remodeling by inducing EMT." (PMID 38022556, 2023). "Thus, we speculate that sema7a may promote chronic airway inflammation and AR in asthma." (PMID 38022556, 2023). "Western blotting and RT-PCR showed that Sema7a and Integrin-β1 expression were significantly increased in lung tissue from the ovalbumin (OVA)-induced asthma model." (PMID 38022556, 2023).
autoimmune conditions (1 paper, 2018). "The seminal paper by Czopik and associates extensively examined a costimulatory role of Sema7A and demonstrated that it acts as an inhibitor of T cell activation and essential constrainer of T cell-mediated autoimmunity." (PMID 30134791, 2018). "Ultimately, the authors of both studies suggested that Sema7A might be a potential therapeutic target to treat multiple sclerosis (MS) and other autoimmune conditions." (PMID 30134791, 2018).
B-cell lymphoma (1 paper, 2025). "Top proteins that were consistently associated with B-cell lymphoma across the EPIC, ARIC and UK Biobank cohorts included: CXCL13, sCD23, FCRL1, FCRL3, SEMA7A, CD72, CD48, LY9 and VCAM1." (PMID 40894013, 2025). "Strikingly, all the top proteins associated with B-cell lymphoma development (sCD23, FCMR, FCRL1, FCRL3, SELL, SEMA7A and SEMA4A) were most strongly associated with CLL development, suggesting CLL was a major driver of the top protein associations observed in the grouped analysis." (PMID 40894013, 2025).
bladder cancer (1 paper, 2025). "In the TCGA-pan cancer datasets, ACC is with pancreatic adenocarcinoma (PAAD) and bladder cancer (BLCA) among the cancers expressing the highest levels of SEMA7A." (PMID 40647379, 2025).
cardioembolic stroke (1 paper, 2024). "In CE, upregulation of Sema7A interaction with endothelial integrin β1 or glycoprotein Ib mediates downstream signaling pathways to form a thrombus inducing cardioembolic stroke." (PMID 38373967, 2024).
cerebrovascular diseases (1 paper, 2018). "Examples of these efforts may include the studies with prospective design to explore the prognostic value of Sema7A for major cardiovascular outcomes and targeting Sema7A to provide a novel avenue in combating cardio-cerebrovascular diseases." (PMID 30555351, 2018).
cholestasis (1 paper, 2023). Impairment of the bile flow caused by obstruction within the liver, or outside the liver in the bile duct system. "SEMA7A is involved in cell signaling and migration, and mutations in this gene can lead to disrupted hepatocyte polarity, causing cholestasis and other liver-related complications." (PMID 37324459, 2023).